DLX5 (distal-less homeobox 5)
Description:
Transcriptional factor involved in bone development. Acts as an immediate early BMP-responsive transcriptional activator essential for osteoblast differentiation. Stimulates ALPL promoter activity in a RUNX2-independent manner during osteoblast differentiation. Stimulates SP7 promoter activity during osteoblast differentiation. Promotes cell proliferation by up-regulating MYC promoter activity. Involved as a positive regulator of both chondrogenesis and chondrocyte hypertrophy in the endochondral skeleton. Binds to the homeodomain-response element of the ALPL and SP7 promoter. Binds to the MYC promoter. Requires the 5'-TAATTA-3' consensus sequence for DNA-binding.
Synonyms: SHFM1; SHFM1D
Tractability: PROTAC: ubiquitination databases record sites on it.
Gene: Protein-coding gene on chromosome 7 (97,020,396 to 97,024,950, reverse strand). Ensembl gene ENSG00000105880.
Subcellular location: Nucleus
Subcellular location (Human Protein Atlas): Nucleoplasm
Pathways (Reactome):
Developmental Biology: Developmental Lineage of Mammary Stem Cells; Specification of the neural plate border
Gene expression (Transcription): Regulation of RUNX2 expression and activity
Gene Ontology:
Molecular function: sequence-specific double-stranded DNA binding; transcription cis-regulatory region binding; DNA-binding transcription activator activity, RNA polymerase II-specific; DNA-binding transcription factor activity, RNA polymerase II-specific; RNA polymerase II cis-regulatory region sequence-specific DNA binding; DNA binding; HMG box domain binding
Biological process: cell population proliferation; positive regulation of DNA-templated transcription; BMP signaling pathway; cell differentiation; embryonic skeletal system development; endochondral ossification; nervous system development; osteoblast differentiation; positive regulation of transcription by RNA polymerase II; regulation of transcription by RNA polymerase II; skeletal system development; regulation of DNA-templated transcription
Cellular component: chromatin; nucleus; cytoplasm
Genetic constraint (gnomAD): Loss-of-function variants: 8 observed, 28.97 expected, observed/expected ratio (o/e) 0.28, 90% interval 0.16 to 0.5. The upper end of that interval is the gene's LOEUF score, 0.5, which puts it in group 2 of 6, group 1 being the genes least tolerant of losing a copy. Missense variants: 339 observed, 402.96 expected, observed/expected ratio (o/e) 0.84, 90% interval 0.77 to 0.92. Synonymous variants: 178 observed, 175.69 expected, observed/expected ratio (o/e) 1.01, 90% interval 0.9 to 1.15.
Homologues: Orthologues: chimpanzee DLX5 (100% identical), macaque DLX5 (99% identical), dog DLX5 (98% identical), guinea pig DLX5 (97% identical), pig DLX5 (97% identical), mouse Dlx5 (97% identical), rat Dlx5 (96% identical), tropical clawed frog dlx5 (79% identical), zebrafish dlx5a (74% identical), rabbit DLX5 (68% identical), Drosophila melanogaster Dll (34% identical), Caenorhabditis elegans ceh-43 (30% identical). Paralogues in human: DLX3 (55% identical), DLX2 (48% identical), DLX1 (37% identical), DLX6 (34% identical), DLX4 (30% identical), NANOG (20% identical), NANOGP8 (20% identical), BSX (18% identical), VENTX (15% identical).
Diseases named in the same sentence as DLX5 in open-access papers:
DLX5 is named in the same sentence as 102 diseases in open-access papers, as found by Europe PMC text mining. Sharing a sentence is not in itself a finding about the gene and the disease. The quoted sentences say what the papers report.
osteosarcoma (10 papers, 2011 to 2025). A usually aggressive malignant bone-forming mesenchymal neoplasm, predominantly affecting adolescents and young adults. "DLX5 can promote ovarian cancer cell proliferation by enhancing the IRS-2-AKT pathway; moreover, in osteosarcoma, DLX5 can activate the NOTCH signaling pathway to promote tumor progression." (PMID 38760791, 2024). "The aberrations of DLX5 were validated in five of the cell lines and five osteosarcoma tumour samples using quantitative real-time PCR and RT-PCR." (PMID 23144859, 2012). "DLX5, a transcription factor involved in bone formation, is downregulated in fibroblastic osteosarcoma, and reflects the lower amounts of matrix present in fibroblastic osteosarcoma." (PMID 21933437, 2011). "DLX5 exerts oncogenic effects in osteosarcoma through NOTCH1 activation, and given that the Notch pathway drives TGF-β–induced EMT, DLX2 may contribute to EMT through similar mechanisms." (PMID 41244921, 2025). "DLX5 promotes osteosarcoma progression by activating the NOTCH signaling pathway." (PMID 38317839, 2024). "In human osteosarcoma cells (MG63 cells), the expression of Runx2 was concurrently increased with Dlx5, Mage-D1 and Necdin41." (PMID 36585447, 2022). "DLX5 inactivation by siRNA in HOS and MG-63 OS cell lines inhibits cell growth and osteosarcoma progression, inducing apoptosis an both in vitro and in vivo." (PMID 36291143, 2022). "In a first study, human osteosarcoma MG63 cells, exhibiting an immature phenotype reminiscent of MSCs,34 were used to assess the biological effect of DLX5 or RUNX2 mRNA transfer." (PMID 26528487, 2015). "On the contrary, DLX5 overexpression did not induce changes in miR-200 expression, either in SH-SY5Y or in GN11 (neuroendocrine) or in U2OS (osteosarcoma) cells (data not shown)." (PMID 25937343, 2015).
ovarian carcinoma (10 papers, 2011 to 2025). A malignant neoplasm originating from the surface ovarian epithelium. "A few studies reported that upregulation of DLX5 promotes ovarian cancer cell proliferation by enhancing IRS‐2‐AKT signalling." (PMID 39706818, 2024). "In human ovarian cancer cells, it has been found that DLX5 is essential for regulating AKT signaling, thereby promoting cell proliferation and survival." (PMID 37035196, 2023). "We found that overexpression of DLX5 promoted ovarian cancer cell proliferation by augmenting IRS-2/AKT signaling." (PMID 34203994, 2021). "In a screen of the NCI 60 cancer cell line panel, DLX5 was frequently upregulated in cell lines derived from several tumor types, including ovarian cancer, and data from The Cancer Genome Atlas indicate that DLX5 is a poor prognosis marker in ovarian cancer." (PMID 34203994, 2021). "It has been documented that DLX5 upregulation promoted ovarian cancer cells growth by activating IRS-2-AKT signaling." (PMID 34277436, 2021). "In humans, DLX5 is aberrantly expressed in lung and ovarian carcinomas and holds promise as a therapeutic target." (PMID 34203994, 2021). "In human ovarian cancer cells, DLX5 is essential for regulating AKT signaling, thereby promoting cell proliferation and survival." (PMID 34203994, 2021). "We previously reported that in human ovarian carcinoma cells, DLX5 transactivates the IRS2 gene via direct binding to the IRS2 promoter, thereby resulting in enhanced AKT signaling." (PMID 28122332, 2017). "In ovarian cancer, DLX5 promotes cell proliferation via upregulation of AKT signaling through the direct transactivation of insulin receptor substrate 2 (IRS2)." (PMID 28122332, 2017). "We previously reported that DLX5 contributes to AKT signaling in human ovarian cancer cells via direct upregulation of IRS2 transcription." (PMID 28122332, 2017). "Furthermore, genetic studies have shown that Dlx5 is involved in the pathogenesis of ovarian cancer, lung cancer, and T-cell lymphoma." (PMID 40003710, 2025). "At the mechanistic level, the pro-tumorigenic functions of DLX5 have been shown to involve positive regulation of the MYC promoter in human lung cancer cells as well as the IRS2 promoter, an IGFIR adapter protein, in ovarian cancer cell lines." (PMID 30412601, 2018).
Anxiety (7 papers, 2018 to 2024). Intense feelings of nervousness, tension, or panic often arise in response to interpersonal stresses. "Modifications of Dlx5/6 expression targeted to mouse GABAergic neurons have permitted an association of anxiety-like, compulsive-like and social behaviours with the allelic dosage of these genes." (PMID 39120293, 2024). "On the other hand, experimental overexpression of Dlx5 in GABAergic neurons results in increased PV-neuron density in the frontal cortex associated with increased anxiety." (PMID 39120293, 2024). "In parallel, we observe that Dlx5/6 expression levels in GABAergic neurons are also linearly associated with the intensity of anxiety and compulsivity-like behaviours." (PMID 35681437, 2022). "However, the pan-interneuron Dlx5/6 mutants exhibited deficits in marble burying, a task that is susceptible to altered anxiety and OCD-like behaviors as well as changes in fine motor function." (PMID 32343226, 2020). "Targeted inactivation of Dlx5/6 in mouse GABAergic neurons alters behaviour, vocal socialisation and metabolism with a reduction in anxiety-like and obsessive-compulsive-like behaviours." (PMID 39120293, 2024). "Since both anxiety and prefrontal density of PV-interneurons are correlated with depression-like behaviours, we performed a forced swim test on Dlx5/6VgatCre/+, Dlx5/6VgatCre and GABAergicDlx5/+ mice to measure their depressive-like status." (PMID 39120293, 2024). "In these experiments, alterations in Dlx5/6 expression were present since the embryonic stages and lasted throughout life, with increased or reduced anxiety- and depressive-like phenotypes depending on their genotypes." (PMID 39120293, 2024). "We have recently shown that targeted inactivation of Dlx5 and Dlx6 in mouse GABAergic interneurons affect behaviour, vocal socialisation and metabolism with a reduction in anxiety-like and obsessive-compulsive-like behaviours." (PMID 35681437, 2022). "The results of these studies are consistent with our observation that Ank1F/F;Dlx5/6-Cre mice have both reduced anxiety and a significant reduction in PNN density." (PMID 34180393, 2021). "In agreement with previous work, we found no significant impairments in percentage of time spent in the open arms of the elevated plus maze task, a measure of anxiety, for the Dlx5/6, VIP, PV, or SST mutants compared to controls." (PMID 32343226, 2020). "These behavioral phenotypes are clearly indicative of low anxiety in Plcg1F/F; Dlx5/6-Cre mice." (PMID 31780806, 2019). "Among these changes, reduced anxiety and attenuated freezing behavior differ from the typical phenotypes of epileptic mice mostly exhibiting heightened anxiety and increased freezing, implicating that aged Plcg1F/F; Dlx5/6-Cre mice are different from common epileptic mouse models." (PMID 31780806, 2019). "In addition, aged Plcg1F/F; Dlx5/6-Cre mice exhibit other behavioral alterations, including hypoactivity, reduced anxiety, and fear memory deficit." (PMID 31780806, 2019). "Interestingly, Plcg1F/F; Dlx5/6-Cre mice spent less time only in exploring the peripheral zone of the open field, possibly indicating the decreased level of anxiety." (PMID 31780806, 2019). "The present findings suggest that the expression levels of DLX5/6 and DLX6-AS1, regulating differentiation and function of Parvalbumin-positive neurons in the adult brain, also affects anxiety and depression and pave the way for further analyses on the mechanism of action of antidepressants." (PMID 39120293, 2024).
lung carcinoma (7 papers, 2014 to 2025). "It has been reported that DLX-5 overexpression in lung cancer cells is associated with tumor size and predictive of poor prognosis and NSCLC cell proliferation." (PMID 25411851, 2014). "DLX5 (distal-less homeobox 5) is mainly related to embryonic and postnatal development and cell differentiation, and it is overexpressed in lymphomas and lung cancer." (PMID 36661515, 2023). "A study on lung cancer has shown that lysine demethylase 4A (KDM4A) increases the transcriptional activity of DLX5 by promoting the demethylation of DLX5." (PMID 34409024, 2021). "In lung cancer, upregulated expression of DLX5 is predictive of a poor prognosis, and knockdown of DLX5 suppresses lung tumor cell proliferation." (PMID 28122332, 2017). "DLX5 is methylated in early stage lung cancers, suggesting that it is only deregulated in lung cancer progression, and it is not in PAH, in which it induces the expression of MYC and β-catenin, promoting cell proliferation and metastasis." (PMID 36661515, 2023). "According to the TRN analysis, SOX4 can be regulated by HOXC6, whereas DLX5 can be regulated by SOX4, FOXM1, and ETV4, and according to the co-regulatory network analysis, they both participate in the formation of TF complexes in both subtypes of lung cancer (NSCLC and SCLC)." (PMID 39228892, 2024). "In lung cancer, BMP5 is a common gene but it is downregulated, as are TGF-β receptors and SMADs; therefore, none of them may be involved in the regulation of SOX4 and DLX5 expression." (PMID 39228892, 2024).
lymphoma (7 papers, 2010 to 2023). A malignant (clonal) proliferation of B- lymphocytes or T- lymphocytes which involves the lymph nodes, bone marrow and/or extranodal sites. "In this investigation, we found that all lymphomas from Lck-Dlx5 mice have loss of Pten protein expression due to mutation/deletion or epigenetic silencing, resulting in constitutive activation of Akt." (PMID 28122332, 2017). "Furthermore, lymphoma cells from Lck-Dlx5;Lck-MyrAkt2 mice had elevated expression of genes encoding components of the Srebf2 pathway, and their expression was suppressed when β-catenin/Tcf inhibitors were used." (PMID 32985581, 2020). "Further study by RNA-seq analysis has demonstrated that the cholesterol biosynthesis pathway is highly upregulated in lymphoma cells from Lck-MyrAkt2;Dlx5 mice." (PMID 34203994, 2021). "RNA-seq analysis performed on lymphomas from Lck-Dlx5;Lck-MyrAkt mice revealed upregulation of genes involved in the Wnt and cholesterol biosynthesis pathways." (PMID 32985581, 2020). "Immunoblot analysis of lymphoma cells from Lck-Dlx5;Lck-MyrAkt2 mice demonstrated that PFK118-310 also promotes caspase 3 activity and consequent Parp cleavage." (PMID 32985581, 2020). "Combined RNA-seq and ChIP-seq analysis of lymphomas from Lck-Dlx5;Lck-MyrAkt mice demonstrated that β-catenin directly regulates genes involved in sterol regulatory element binding transcription factor 2 (Srebf2)-cholesterol synthesis." (PMID 32985581, 2020). "An MTS assay demonstrated that lymphoma cells from these double transgenic mice were highly sensitive to PFK118-310-induced cell death when compared to lymphoma cells from Lck-Dlx5 mice." (PMID 32985581, 2020). "To further discern factors potentially unique to Dlx5-driven lymphomagenesis, we compared gene expression profiles in lymphomas from Lck-Dlx5 mice with those of Lck-MyrAkt2 animals." (PMID 28122332, 2017). "Immunohistochemistry also confirmed that Notch1, Notch3, Hes1, Myc and phospho (active)-Akt are upregulated in primary and metastatic lymphomas from Lck-Dlx5 mice." (PMID 28122332, 2017). "Real-time RT-PCR confirmed that Notch1, Notch3, Hes1 and Myc mRNA levels were upregulated in Lck-Dlx5 lymphomas, when compared with those of WT thymic T-cells and Lck-MyrAkt2 lymphomas." (PMID 28122332, 2017). "To directly block the Notch pathway, we transduced GFP-coupled Dominant negative mastermind (DN-MM) into Lck-Dlx5 lymphoma cells, which resulted in reduced cell viability." (PMID 28122332, 2017). "This comparison revealed enhanced expression of Notch and histone cluster genes specifically in Lck-Dlx5 lymphomas." (PMID 28122332, 2017). "Array-CGH analysis uncovered unique rearrangements of Tcrb and Tcra loci in each Lck-Dlx5 lymphoma examined, indicative of monoclonal proliferation of a malignant T cell in each tumor." (PMID 28122332, 2017). "Inhibition of Akt or Notch signaling in Lck-Dlx5 lymphoma cells by transduction of Pten or DN-MM, respectively, markedly suppressed tumor growth in vivo." (PMID 28122332, 2017). "Karyotypic analysis revealed that trisomy 15 was the only recurring abnormality in Lck-Dlx5 lymphomas." (PMID 28122332, 2017). "In contrast, aberrant expression of Dlx1as, and Notch were a specific feature of Lck-Dlx5 lymphomas, suggesting that a Dlx5-Notch-Myc axis plays a critical role in the pathogenesis of these tumors." (PMID 28122332, 2017). "Treatment with DAPT or γ-secretase inhibitor XXI for 2 days strongly suppressed the proliferation of Lck-Dlx5 lymphoma cells, as shown by cell cycle analysis." (PMID 28122332, 2017). "The Lck-Dlx5 lymphoma cells formed nodules primarily in liver and spleen 2 weeks after intravenous injection." (PMID 28122332, 2017).